ZFPL1 (zinc finger protein like 1)
Description:
Required for cis-Golgi integrity and efficient ER to Golgi transport. Involved in the maintenance of the integrity of the cis-Golgi, possibly via its interaction with GOLGA2/GM130.
Synonyms: D11S750; MCG4
Tractability: Antibody: UniProt predicts a signal peptide or a membrane-spanning region. PROTAC: ubiquitination databases record sites on it; its protein half-life has been measured.
Gene: Protein-coding gene on chromosome 11 (65,084,210 to 65,088,398, forward strand). Ensembl gene ENSG00000162300.
Subcellular location: Golgi apparatus, cis-Golgi network membrane
Subcellular location (Human Protein Atlas): Golgi apparatus
Gene Ontology:
Molecular function: protein binding; DNA binding; zinc ion binding
Biological process: regulation of DNA-templated transcription
Cellular component: Golgi apparatus; nucleus
Genetic constraint (gnomAD): Loss-of-function variants: 28 observed, 33.31 expected, observed/expected ratio (o/e) 0.84, 90% interval 0.62 to 1.15. The upper end of that interval is the gene's LOEUF score, 1.15, which puts it in group 5 of 6, group 1 being the genes least tolerant of losing a copy. Missense variants: 386 observed, 435.75 expected, observed/expected ratio (o/e) 0.89, 90% interval 0.81 to 0.96. Synonymous variants: 165 observed, 177.53 expected, observed/expected ratio (o/e) 0.93, 90% interval 0.82 to 1.06.
Homologues: Orthologues: chimpanzee ZFPL1 (99% identical), dog ZFPL1 (94% identical), pig ZFPL1 (93% identical), rabbit ZFPL1 (93% identical), rat Zfpl1 (93% identical), mouse Zfpl1 (92% identical), guinea pig ZFPL1 (91% identical), macaque ZFPL1 (85% identical), tropical clawed frog zfpl1 (62% identical), zebrafish zfpl1 (56% identical), Drosophila melanogaster CG5382 (43% identical), Caenorhabditis elegans Y45G12B.2 (41% identical).
Diseases named in the same sentence as ZFPL1 in open-access papers:
ZFPL1 is named in the same sentence as 5 diseases in open-access papers, as found by Europe PMC text mining. Sharing a sentence is not in itself a finding about the gene and the disease. The quoted sentences say what the papers report.
colorectal cancer (1 paper, 2025). A primary or metastatic malignant neoplasm that affects the colon or rectum. "While this study establishes a pivotal role for ZFPL1 in promoting colorectal cancer progression and metastasis through ASS1 stabilization, urea cycle reprogramming, and immunomodulation, several limitations remain to be addressed." (PMID 41216870, 2025).
tumour (3 papers, 2018 to 2025). "Crucially, ZFPL1 deficiency remodels the tumor microenvironment by reducing immunosuppressive populations‐M2 macrophages, and promoting pro‐inflammatory M1 polarization." (PMID 41216870, 2025). "Western blot analysis of 8 paired CRC and normal tissue samples consistently demonstrated elevated ZFPL1 protein levels in tumor tissues." (PMID 41216870, 2025). "Functionally, ZFPL1 promotes tumor proliferation, invasion, and migration both in vivo and in vitro." (PMID 41216870, 2025). "This orthogonal validation approach revealed significantly higher ZFPL1 expression in tumor cells (CK8 positive) compared to adjacent tissues." (PMID 41216870, 2025). "To further explore the role of ZFPL1 in vivo, we established a subcutaneous tumor model by injecting MC38 cells with ZFPL1 knockdown (sh‐ZFPL1) or control (sh‐NC) into C57BL/6 mice." (PMID 41216870, 2025). "Zinc finger protein like 1 (ZFPL1) was positive in 8/30 tumours; however, in 7 of them, only few predominantly keratinized SCC cells stained; only one carcinoma was diffusely positive." (PMID 29976164, 2018). "Together, our integrated multi‐omics analysis establishes ZFPL1 as a tumor cell‐enriched gene in CRC, validated across scRNA‐seq datasets and protein‐level assays, whose high expression correlates with aggressive clinicopathological features and poor patient survival outcomes." (PMID 41216870, 2025). "However, considering the pivotal role of TME in cancer development and therapeutic response, there remains a critical knowledge gap regarding ZFPL1's immunomodulatory functions within the tumor microenvironment landscape." (PMID 41216870, 2025). "Notably, ZFPL1 demonstrated consistent enrichment in tumor cells from both primary and metastatic sites(PN, MN), while showing negligible expression in adjacent normal tissues." (PMID 41216870, 2025). "Predictably, we found that the normally strict basal positioning of nuclei, apical positioning of intracellular vesicles and the supranuclear localisation of the Golgi resident protein ZFPL1 and the centrosome marker pericentrin in wild-type intestinal epithelia was lost in ApcMin/− tumour cells." (PMID 33335067, 2021).
cancer (2 papers, 2018 to 2025). A tumor composed of atypical neoplastic, often pleomorphic cells that invade other tissues. "Subsequent KEGG pathway analysis identified significant enrichment of urea cycle metabolism, glucose metabolism, and cancer‐related pathways, suggesting potential involvement of these pathways in ZFPL1‐mediated CRC progression." (PMID 41216870, 2025).
ZFPL1 also shares sentences with these, for which no sentence is quoted: prostate carcinoma (2 papers); endometrial cancer (1).